YWHAZ (tyrosine 3-monooxygenase/tryptophan 5-monooxygenase activation protein zeta)
Diseases named in the same sentence as YWHAZ in open-access papers (continued):
Sharing a sentence is not in itself a finding about the gene and the disease.
breast carcinoma (continued). "Besides, the expression of YWHAZ could be negatively regulated by miR-30c in cervical cancer, by miR-544 in breast cancer, and by miR-613 in HCC 58-60." (PMID 32127952, 2020). "YWHAZ has been shown to stimulate lung cancer cell proliferation and metastasis and promote the invasion of breast cancer cells, suggesting that it might serve as a therapeutic target of breast cancer." (PMID 32419250, 2020). "Our previous research revealed that DAAM1 was highly expressed in breast cancer tissues and was mediated by YWHAZ protein, and the cooperation between YWHAZ and DAAM1 contributed to breast cancer metastasis." (PMID 36311172, 2022). "Regarding the combination of hepatic and breast cancer cell lines, the geNorm indicated UBC as the most stable reference gene, and the RefFinder ranked UBC and YWHAZ as two stable ones in both cellular and exosomal content." (PMID 34752497, 2021). "Our results overally indicated that GAPDH, YWHAZ, and UBC were the most stable reference genes in breast cancer cell lines, including MCF7, SKBR3 and MDA-MB231, and B2M and ACTB were the least stable ones." (PMID 34752497, 2021). "In breast cancer, silencing of LAPTM4B and YWHAZ gene sensitized tumor cells to anthracyclines, while overexpression of these genes induced drug resistance." (PMID 32127952, 2020). "Our data suggest that TP63, YWHAZ, BRCA1, CCND2, YWHAG, and HIPK2 can be potential genetic markers of prognostic assessment, immune infiltration and chemotherapeutic drug sensitivity in breast cancer patients." (PMID 36673982, 2023). "We found that the vast majority of IGF regulators were upregulated in various cancers, such as HRAS and YWHAZ in lung squamous cell carcinoma (LUSC), SHC1 in kidney cancer, PRKCZ in bladder cancer (BLCA) and in breast cancer (BRCA), and NCK2 in cholangiocarcinoma (CHOL)." (PMID 35935986, 2022). "In particular, YWHAZ overexpression, ErbB2 overexpression, and positive lymph node status were seen to be independent prognostic factors in breast cancer." (PMID 32127952, 2020). "Moreover, YWHAZ, UBC, and GAPDH showed the highest stability in breast cancer cell lines." (PMID 34752497, 2021). "Finally, gene expression data analysis from the breast cancer cell line dataset and copy number variation from the cancer cell line encyclopedia dataset similarly demonstrated increased expression/CN variation of CCND1 and YWHAZ in TNBC cell lines." (PMID 34350123, 2021).
lung carcinoma (22 papers, 2009 to 2025). "Additionally, YWHAZ bound with partitioning defective protein 3 (Par3) in lung cancer and loss of Par3 enhanced the interaction of YWHAZ and Tiam1, subsequently activating Rac1 and promoting cancer cell metastasis." (PMID 32127952, 2020). "Specifically, circ0515 promotes lung cancer progression through the miRNA-328-3p/YWHAZ/AKT signaling axis." (PMID 40617805, 2025). "YWHAZ has also been shown to mediate lung cancer malignancy and β-catenin protein through its complex with β-catenin." (PMID 39267750, 2024). "Overexpression of YWHAZ can also be found in adenocarcinoma of the esophagogastric junction, lung cancer, and intrahepatic cholangiocarcinoma; thus, overexpression of YWHAZ is related to invasiveness and drug resistance in multiple types of tumors." (PMID 35027933, 2022). "We found that the expression levels of YWHAZ were negatively correlated with the expression levels of miR-375-3p in lung cancer tissues (n=22)." (PMID 33968726, 2021). "Emerging evidence has shown that YWHAZ plays critical roles in the progression of many types of tumors, including lung cancer." (PMID 34277626, 2021). "Immunoprecipitation and immunofluorescence analysis revealed that YWHAZ formed complex with Hsp27 protein, colocalizing in the cytoplasm of lung cancer cells." (PMID 32127952, 2020). "EPB41L3 (DAL1) binds to YWHAZ, and the YWHAZ/β-catenin axis promoted epithelial-mesenchymal transition and lung cancer metastasis." (PMID 27534621, 2016). "YWHAZ protein expression is well known to be related to advanced disease grade and poor clinical outcome in lung cancer patients." (PMID 26629988, 2015). "YWHAZ previously was thought as a reference gene in many cell lines, recently it was found to play a major role in YWHAZ/beta-Catenin Axis and promote Epithelial-Mesenchymal Transition and Lung Cancer Metastases." (PMID 24597767, 2014). "Additionally, higher YWHAZ expression was significantly correlated with poor prognosis in lung cancer patients." (PMID 40617805, 2025). "Conversely, knockdown of circ0515 inhibited lung cancer cell proliferation, an effect that could be rescued by overexpressing YWHAZ." (PMID 40617805, 2025). "YWHAZ has been reported to stabilize β-catenin by binding competitively with β-TrCP binding sites to protect β-catenin from ubiquitination-dependent degradation in lung cancer." (PMID 39020380, 2024). "Polymorphisms in ICOS have been associated with pre-disposition to non-small cell lung cancer, while over-expression of YWHAZ is known to enhance proliferation and migration of lung cancer cells through induction of epithelial-mesenchymal transitions via beta-catenin signaling." (PMID 27145341, 2016). "Mechanistically, circ0515 functions as a molecular sponge for miR-328-3p, leading to the upregulation of its downstream target gene YWHAZ, which activates the AKT signaling pathway to promote lung cancer cell proliferation and migration." (PMID 40617805, 2025). "On one hand, circ0515 acts as a molecular sponge for miRNA-328-3p, upregulating the downstream target gene YWHAZ, activating the AKT signaling pathway, and significantly enhancing the proliferation and migration of lung cancer cells." (PMID 40617805, 2025). "On one hand, circ0515 acts as a molecular sponge for miRNA-328-3p, upregulating its downstream target gene YWHAZ, thereby activating the AKT signaling pathway and significantly promoting lung cancer cell proliferation and migration." (PMID 40617805, 2025). "YWHAZ is involved in promoting EMT and lung cancer metastasis and was found to be a reliable prognostic biomarker for NSCLS." (PMID 35512017, 2022). "Thus, the YWHAB, YWHAQ, and YWHAZ proteins involved in various biological processes and signalling pathways, could be new targets for future cancer therapy, especially in targeting CSCs in lung cancer." (PMID 33670440, 2021).
lung carcinoma (continued). "Recent evidence has identified a novel function of YWHAZ in activating β-catenin mediated transcription to promote EMT and lung cancer metastasis." (PMID 34439128, 2021). "Another report showed that the formation of β-catenin/YWHAZ complex suppressed β-catenin from binding of βTrCP, leading to an increase in β-catenin stability and promoting EMT in lung cancer." (PMID 26497204, 2015).
hepatocellular carcinoma (20 papers, 2012 to 2024). A malignant tumor that arises from hepatocytes. "In a previous study, hsa-miR-451a was reported to inhibit the proliferation and migration of hepatocellular carcinoma cells by targeting gene YWHAZ." (PMID 37754250, 2023). "MIR4435-2HG has, for example, been found to promote hepatocellular carcinoma proliferation and metastasis by sponging miR-22-3p to liberate YWHAZ mRNA transcripts." (PMID 37355516, 2023). "Other genes upregulated were BCL2A1, an anti-apoptotic player, usually implicated in cancer progression, as well as YWHAZ, YWHAH, and IRS2, which participates in the development of insulin resistance as well as hepatocellular carcinoma." (PMID 36612019, 2022). "Studies have found that miR-451 can inhibit hepatocellular carcinoma proliferation and metastasis by targeting YWHAZ." (PMID 31640760, 2019). "YWHAZ enhances metastasis and is related to the poor survival in hepatocellular carcinoma." (PMID 33968726, 2021). "YWHAZ has been identified as the target gene of miR-613 in hepatocellular carcinoma." (PMID 34453038, 2021). "MiR-613 functions as a tumor suppressor in hepatocellular carcinoma by targeting YWHAZ." (PMID 31019537, 2019). "In hepatocellular carcinoma, ITGB1 regulated the cell cycle process via the PXN/YWHAZ/AKT pathway, promoting hepatocellular carcinoma progression." (PMID 38183097, 2024).
schizophrenia (14 papers, 2011 to 2024). A major psychotic disorder characterized by abnormalities in the perception or expression of reality. "YWHAZ is involved in dopamine production and has been associated with behavioral changes in patients with schizophrenia and cognitive impairment in patients with bipolar disorder." (PMID 40051599, 2024). "In humans, genetic studies have associated YWHAZ polymorphisms with major depression and schizophrenia." (PMID 39146369, 2024). "Other genetic and post-mortem mRNA studies have identified genes for the 14-3-3 isoforms—including the gene YWHAZ, the encoding of which was discovered by us in the 14-3-3 ζ protein—as a potential susceptibility gene for schizophrenia." (PMID 37894929, 2023). "In addition to being located on a susceptible locus, genetic studies have releveled associations between SNPs and ultra-rare variants of the YWHAZ gene and schizophrenia." (PMID 35359567, 2022). "Also, when 14-3-3 genes are considered individually, rare variants in the YWHAZ gene are shown to contribute to schizophrenia." (PMID 32545830, 2020). "Knockout mice for YWHAZ present behavioral and cognitive alterations (hyperactivity, impaired memory) similar to those observed in patients affected by schizophrenia, autism and other psychiatric disorders." (PMID 39146369, 2024). "YWHAZ, which encodes the 14–3-3 protein, has been found to be altered in patients with MDD, bipolar disorder, and schizophrenia." (PMID 38049858, 2023). "YWHAZ has been well-studied in schizophrenia, its gene product belongs to the 14-3-3 family of proteins which mediate signal transduction by binding to phosphoserine-containing proteins." (PMID 25608650, 2015). "Thus, both YWHAZ and YWHAH genes have been considered as schizophrenia risk genes because they are located chromosomally close to loci that have been genetically associated with schizophrenia." (PMID 35359567, 2022). "Gene-based analyses using publicly available datasets revealed that common variants in YWHAE contribute to schizophrenia (p = 6.6 × 10−7), whereas ultra-rare variants were found enriched in ASD across the 14-3-3 genes (p = 0.017) and in schizophrenia for YWHAZ (meta-p = 0.017)." (PMID 32545830, 2020). "However, in line with our results, higher levels of expression of YWHAB, YWHAE, YWHAG and YWHAZ have been described in the brains of schizophrenia patients compared with controls." (PMID 32555255, 2020). "These PPIs are of particular interest since genetic association studies have previously implicated YWHAE, YWHAH, and YWHAZ with schizophrenia and bipolar disorder and the PBRM1 locus has surpassed genome-wide significance in both schizophrenia and bipolar disorder GWASs." (PMID 27142060, 2016). "The other YWHAZ abnormalities were the interactions with RNPS1 and LGALS1 in schizophrenia; the interactions with MYCBP2, PRDX1 or TP1l in bipolar disorder; the interactions with RPLP2 and VIM in major depression; and the interactions with RPLP0 in both schizophrenia and major depression." (PMID 22373040, 2011). "Interestingly, five of these genes showed alterations in expression in both ASD and schizophrenia: YWHAB, YWHAE, YWHAH and YWHAZ showed decreased expression whether SFN showed increased expression in both disorders." (PMID 32545830, 2020). "All three sets of module genes include well-studied candidate genes for schizophrenia (e.g., DTNBP1), glutamate receptors (e.g., GRIN1), several genes located in the MHC region (e.g., HIST1H1A, HIST1H1C, HIST1H2AB, HIST1H2BB, HLA-E), and genes from the 14-3-3 protein family (e.g., YWHAQ, YWHAZ)." (PMID 23134571, 2012). "However, we did not observe any significant changes in YWHAZ in these early postnatal stress-based models, suggesting that later stress in adolescence or adult life could be responsible for the altered levels detected in postmortem cerebellum in schizophrenia." (PMID 34576238, 2021).
colorectal cancer (13 papers, 2015 to 2024). A primary or metastatic malignant neoplasm that affects the colon or rectum. "Another upregulated protein, YWHAZ, also known as 14-3-3ζ, is commonly overexpressed in a variety of neoplasms and plays a critical role in various cancers, including breast, lung, prostate, hepatocellular, and colorectal cancers." (PMID 35371990, 2022). "It is observed that the expression of YWHAZ is increased in 46 colorectal cancer (CRC) tissues." (PMID 33718221, 2021). "Our results demonstrated that miR-1-3p suppresses colorectal cancer cell proliferation and metastasis through regulating YWHAZ-mediated EMT, which may support a novel therapeutic strategy for CRC patients." (PMID 33718221, 2021). "Similarly, long non-coding RNA SNHG14, acting as a miR-206 sponge and decreasing its expression, increased YWHAZ expression in cervical cancer 62 and long non-coding RNA LINC00858 regulated YWHAZ by inhibiting miR-22-3p in colorectal cancer." (PMID 32127952, 2020). "LINC00858 expression was observed to be up-regulated in colorectal cancer (CRC), osteosarcoma and non-small cell lung cancer (NSCLC) tissues, and associated with poor prognosis, which is in line with our hypothesis, and it exerted its functional effect through the miR-22-3p/YWHAZ axis in CRC." (PMID 32419983, 2020).
prostate carcinoma (11 papers, 2013 to 2023). A carcinoma that arises from epithelial cells of the prostate gland. "Proteomic analysis in human prostate cancer and benign prostatic hyperplasia samples have revealed association between over-expression of YWHAZ and NDRG1 and poor prognosis based on Gleason scores." (PMID 37249826, 2023). "In the study of prostate cancer, the 14-3-3 family of YWHAZ, which is associated with the prognosis of metastatic prostate cancer, can be used as a target for prostate cancer treatment." (PMID 31496919, 2019). "The increased expression of YWHAZ promotes the proliferation, migration, and resistance to apoptosis of prostate cancer cells, while the downregulation of YWHAZ significantly affects the invasiveness of tumor cells." (PMID 35027933, 2022). "One study found that TRIP13 promoted the proliferation, migration, and invasion and EMT of prostate cancer cells through regulation of tyrosine 3-monooxygenase/tryptophan 5-monooxygenase activation protein zeta (YWHAZ)." (PMID 36268276, 2022). "To verify the role of myosin 1C isoform A mRNA expression as a putative prostate cancer marker we performed RT qPCR normalized by three reference genes (GAPDH, YWHAZ, HPRT1) on PC3, RWPE-1, LNCaP and 22Rv1 cell lines." (PMID 30498638, 2018). "In fact, YWHAZ and NDRG1 expression levels could define two groups of prostate cancer patients with high and intermediate risks of mortality." (PMID 37249826, 2023). "Using a set of three reference genes (YWHAZ, GAPDH, and HPRT1), we analyzed myosin 1C isoform A mRNA expression in a set of cancer and non-cancer cell lines and confirmed the specificity of its expression in prostate cancer cells." (PMID 30498638, 2018).
liver cancer (10 papers, 2012 to 2023). An epithelial or non-epithelial malignant neoplasm that arises from the liver. "Therefore, UBR5 associated with YWHAZ may influence prognosis in patients with liver cancer, and UBR5 could serve as a potential target for liver cancer treatment." (PMID 36388433, 2022). "The YWHAZ protein plays an important role in tumor progression and is involved in many signal transduction pathways in liver cancer." (PMID 37754250, 2023). "Transfecting a YWHAZ expression plasmid into UBR5-suppressed liver cancer cells restored YWHAZ expression." (PMID 36388433, 2022). "YWHAZ expression and liver cancer cell proliferation were affected significantly by interference with UBR5 expression in vitro." (PMID 36388433, 2022). "In hepatic cancer cell lines, the first six stable reference genes were YWHAZ, ACTB, B2M, UBC, HPRT1, and RNA18S." (PMID 34752497, 2021). "Additionally, the TCGA databases confirmed that patients with liver cancer who expressed higher levels of YWHAZ had poorer outcomes." (PMID 36388433, 2022). "In the TCGA data, YWHAZ was highly expressed in liver cancer cohorts." (PMID 36388433, 2022). "Similarly, a panel of five reference genes, namely ACTB, HPRT1, UBC, YWHAZ, and B2M is also recommended for RT-qPCR data normalization of three hepatic cancer cell lines, including Huh7, HepG2, and PLC-PRF5." (PMID 34752497, 2021). "Similarly, YWHAZ was also classified by the RefFinder as the most stable reference gene in the cellular and exosomal content of hepatic cancer cell lines." (PMID 34752497, 2021). "Besides that, a panel of five nominees, including ACTB, HPRT1, UBC, YWHAZ, and B2M showed higher stability than others in hepatic cancer cell lines." (PMID 34752497, 2021). "At present, YWHAZ, JAK2, PDK1 and YAP1 have been identified as cancer relevant direct miR-375 targets in human gastric, esophageal and liver cancer using Luciferase reporter assays." (PMID 24892549, 2014). "By increasing YWHAZ expression, UBR5 promotes liver cancer cell growth." (PMID 36388433, 2022). "Moreover, in hepatic cancer cell lines including Huh7, HepG2, and PLC-PRF5, ACTB, HPRT1, UBC, B2M, and YWHAZ were among the first six stable genes ranked by geNorm, NormFinder, and RefFinder algorithm." (PMID 34752497, 2021).